LGALS1 (galectin 1)
Diseases named in the same sentence as LGALS1 in open-access papers (continued):
Sharing a sentence is not in itself a finding about the gene and the disease.
tumor (continued). "Two critical mediators of TGF-β1 and Galectin-1 have a potential cross talk during the cancer cells progression and tumor-immune escape, but the extensional role of which on the interrelation between PSCs and PCCs in PDAC has not yet well elucidated." (PMID 24595374, 2014). "−0.36) while there was a positive correlation between galectin-1 and galectin-9 protein score in the tumor endothelial cells (corr." (PMID 25259711, 2014). "Galectin-1 and 3 presence in tumor tissue lysates was tested by ELISA in 29 EMCAR patients, 30 US patients, 21 normal/benign endometria and 18 normal myometria." (PMID 24658839, 2014). "Galectin-1 promotes tumor growth and has been described as a cytokine-like factor that participates in the promotion of tumor angiogenesis." (PMID 23530091, 2013). "Galectin-7 reportedly has some effects that oppose those of galectin-1: whereas galectin-1 promotes tumor growth and induces resistance to apoptosis, galectin-7 induces apoptosis in several types of cancer cells." (PMID 23530091, 2013). "Galectin-1 and galectin-3 are highly expressed in tumor tissues and galectin-3 confers high metastatic potential." (PMID 23251263, 2013). "With these important roles outside tumor invasion, galectin-1 proves to be a model molecule in our xenograft study." (PMID 22583806, 2012). "Galectin-1 expression in the tumor cells substitutes endogenous Gal-1 in some extent as demonstrated in Gal-1 knockout mice." (PMID 22844466, 2012). "The standard therapies for GBM – radiation and temozolamide both promote galectin-1 production, a possible survival reaction of the tumor." (PMID 22583806, 2012). "Galectin-1 has a described role in mediating cell adhesion and migration, apoptosis, proliferation, and in facilitating tumour angiogenesis." (PMID 23285151, 2012). "Expression microarray data identified galectin-1 as the most potent marker (p-value 4.0 x 10-8) to identify GBM cells between tumor-brain interface as compared to the tumor core." (PMID 22583806, 2012). "In tumors, galectin-1, -3, -9 are often secreted by tumor cells and monocyte-derived cells, but can also be secreted by activated B or T cells." (PMID 24212939, 2011). "Galectin-1 is involved in cell cycle regulation, apoptosis, cell migration, and tumor evasion of immune responses." (PMID 21765917, 2011). "Expression of galectin-1 is upregulated in various types of tumors and is reported to mediate tumor invasion and metastasis by increasing expression of matrix metalloproteinase MMP-9 and MMP-2 and promoting reorganization of the actin cytoskeleton." (PMID 21687633, 2011). "DAVANAT®, a galactomannan derived from guar gum, has been shown to bind to galectin-1, and to increase the anti-tumor activity of chemotherapy drug 5-fluorouracil in mice." (PMID 24212939, 2011). "In examinated group of 94 patients they showed poorer prognosis for the galectin-1 and galectin-3-expressing tumor in the univariate survival examination and in the multivariate analysis for the galectin-3 positive tumours." (PMID 22024187, 2011). "Comparable cell type-dependent functional divergence has been reported for cell attachment: galectin-1 can stimulate tumor cell attachment to Lam and Fn, but adhesion and spreading of skeletal myoblasts and vascular smooth muscle cells on Lam is inhibited." (PMID 19898636, 2009). "Galectin-1 modulates innate and adaptive immune responses; its over-expression in many types of tumors and/or surrounding tissues promotes tumor progression by inhibition of anti-tumor immune response." (PMID 19340302, 2009). "Blockade of the inhibitory effects of galectin-1 within tumour tissue resulted in reduced tumour mass (an effect which required intact CD4+ and CD8+ T-cell responses) and stimulated the generation of a tumour-specific T-cell response in vivo." (PMID 15785741, 2005). "Here we will review the role of galectin-1 in different steps of tumour progression to evaluate its potential use as a therapeutic target in cancer." (PMID 15785741, 2005).
tumor (continued). "By a combination of in vitro and in vivo experiments using knockdown transfectants, we established a link between galectin-1-mediated immunoregulation and its contribution to tumour-immune escape." (PMID 15785741, 2005). "The immunoregulatory effects of galectin-1 and the correlation between galectin-1 expression in cancer cells and the aggressiveness of these tumours prompted us to investigate the role of galectin-1 in tumor-immune escape." (PMID 15785741, 2005). "Over the past few years, the perceived role of galectin-1 in tumour growth has mirrored the story of Dr Jekyll and Mr Hide." (PMID 15785741, 2005). "Furthermore, we performed Spatalk analysis to elucidate the spatial communication patterns between STMN2+ TAM, CD8+ Tex cells and Tem/Teffe cells in tumor sections, investigating the ligand-receptor interactions (LRIs) between LGALS1 and PTPRC." (PMID 41438751, 2025). "Notably, we observed increased expression of tissue-residence markers (ITGA1, VIM, LGALS1) also in proliferating blood NKs, indicating their inclination toward blood-tumor migration." (PMID 40164596, 2025). "Galectin-1 exerts multiple tumor-promoting functions in GC, actively contributing to the malignant phenotype through regulation of proliferation, migration, invasion, and survival of tumor cells." (PMID 40710343, 2025). "The tumor may express galectin-1 to increase its ability to bind extracellular matrix in blood vessels and distant tissues, which will increase the metastatic potential of the tumor." (PMID 41480246, 2025). "Therefore, it is estimated that the regulation of galectin-1/miR-22-3p expression inhibits tumor growth by regulating the cell cycle in hormone receptor-positive breast cancer." (PMID 39996781, 2025). "Since Galectin-1-glycan lattice formation is sensitive to α2,6 sialylation, ST6GAL1 transfer to tumor-associated immune cells may outcompete the PD-1/PDL1 axis to foster immunosuppressive TME." (PMID 40938891, 2025). "Tumor cells and various host cells show varying levels of Galectin-1 expression." (PMID 40134029, 2025). "Host-derived Galectin-1 mainly supports immune privilege for tumor cells." (PMID 40134029, 2025). "LGALS1 (Galectin-1) functions in cell-matrix interactions and immune response modulation; its downregulation could impact tumor immune evasion and cell communication." (PMID 40090465, 2025). "For example, Galectin-1 is pro-tumorigenic and proangiogenic in tumor progression." (PMID 38881904, 2024). "Galectin-1 could promote tumor cell proliferation by inducing angiogenesis and to induce the tumor cell immune escape." (PMID 39575432, 2024). "In addition, a combination of γδ-T cells and galectin-1 neutralizing antibodies were effective in xenograft models of cervical cancer, further supporting the anti-tumor activity of γδ T cells in this disease." (PMID 38541651, 2024). "Other studies have shown the ability of LGALS1 to induce apoptosis in T-cells and prevent T-cell migration across the tumor endothelium, while the addition of recombinant LGALS1 prolonged the survival of the kidney allografts and was required to induce tolerance in B-cells, in preclinical models." (PMID 39399491, 2024). "Thus, similar to galectin-1 and galectin-3, current findings suggests that galectin-8 can stimulate endothelial cell functions but identifying the exact role of the protein in tumor angiogenesis requires further investigation." (PMID 38990363, 2024). "Moreover, galectin-1 has been shown to induce tumor immune exclusion by increasing the endothelial expression of checkpoint molecules like PD-L1 as well as galectin-9." (PMID 38990363, 2024). "Thus, while additional research is still warranted, elevated galectin-1 expression in tumor endothelial cells appears to predominantly exert immunosuppressive effects." (PMID 38990363, 2024). "Thus, galectin-1 production of cancer cells is elevated by the hypoxic tumor microenvironment, thereby exacerbating the suppressive immune microenvironment." (PMID 37047471, 2023).
tumor (continued). "Similarly, knocking down galectin-1 expression in 4T1 cells led to a diminished proportion of CD4+CD25+Foxp3+ Treg cells within the tumor microenvironment as well as peripheral immune organs." (PMID 37047471, 2023). "Interestingly, LGALS1 has been shown to be highly expressed in GBM tumor cells and drives therapy resistance." (PMID 37791581, 2023). "In a study, γ-δT cells in combination with galectin-1 antibody treatment, significantly suppressed the growth of tumor xenografts in severe combined immunodeficiency (SCID) mice (p < 0.05), although γδ TILs alone showed the ability to inhibit tumor growth in vivo." (PMID 37180106, 2023). "The quadruple action of galectin-1 satisfies the four steps in GC peritoneal metastasis: cancer cells escape from the primary tumor, accumulate in the abdominal cavity to resist anoikis, adhere to distant peritoneum and invade it, and proliferate through neovascularization." (PMID 37328752, 2023). "In another study, Galectin-1 overexpression in HCC cells contributed to tumor growth in vivo." (PMID 37433225, 2023). "However, knockdown of Galectin-1 significantly enhanced the inhibitory effect of CDDP on tumor growth in vivo (P < 0.05)." (PMID 37215991, 2023). "LGALS1 played a crucial role in HCC-associated fibroblasts that orchestrate an inflammatory cancer stem-like cell niche and reprogram the inflammatory tumor microenvironment, thus supporting tumor progression." (PMID 37575948, 2023). "OTX008 could inhibit tumor growth with a strong reduction of galectin-1, Ki-67, and VEGFR-2 expressions in vivo." (PMID 36873388, 2023). "A recent study demonstrated that low concentrations of galectin-1 in the early stage of cancer could elevate the expression of galectin-9 and PD-L1 on tumor endothelial cells via activating STAT1, thus mediating T cell exclusion." (PMID 37047471, 2023). "Accordingly, the effects of galectin-1 on Treg cells are context-dependent, with different tumor-derived galectin-1 may act differently on diverse Treg subsets." (PMID 37047471, 2023). "The number of γδT cells was negatively associated with the progression of CC. γδT cells alone were found to inhibit tumour growth, and if combined with galectin-1 antibody, they could provide a more effective immunotherapy for CC." (PMID 36683048, 2023). "Therefore, the anti-tumor immune activity targeting galectin 1 synergized with anti-PD-L1 antibodies." (PMID 37727791, 2023). "Furthermore, galectin-1 can mediate anti-tumor immunity by reducing transendothelial T cell migration." (PMID 36873388, 2023). "Furthermore, TME galectin-1 (Gal-1) improves tumor cell adhesion, invasiveness, angiogenesis, and immune evasion and contributes to tumor progression." (PMID 36936940, 2023). "Thus, galectin-1 impairs the anti-tumor capacities of Th1 and Th17 cells and induces an immune suppressive microenvironment infiltrated with Th2 cells." (PMID 37047471, 2023). "In colon carcinoma, both tumor cell and stroma-resident galectin-1 could influence tumor growth by controlling the frequency and suppressive activity of CD8+ Treg cells." (PMID 36873388, 2023). "Galectin-1 possibly regulates tumor progression through the monocyte chemotactic protein-1." (PMID 37686288, 2023). "Thus, galectin-1 favors tumor growth by impairing the anti-tumor effects of NK cells and facilitating the infiltration of MDSCs." (PMID 37047471, 2023). "IHC showed that the CDDP treatment increased p-c-Jun, p-ATF2 and Galectin-1 in tumor tissues." (PMID 37215991, 2023). "In this study, LGALS1 showed moderate to strong cytoplasmic and nuclear immunoreactivity in most well-differentiated and poorly differentiated cSCC tumor cells, and some of them were weak staining, while para-cancer normal skin epidermal keratinocytes were almost negative." (PMID 38099574, 2023). "Moreover, chitosan nanoparticles loaded with siRNA targeting Lgals1 have been developed for intranasal delivery to the tumor and its microenvironment." (PMID 37791581, 2023).
tumor (continued). "Galectins have been extensively linked to cancer, specifically controlling cell transformation, apoptosis, proliferation, migration, invasion, and angiogenesis, and LGALS1 has been previously documented to enhance the survival of hematological malignancies by directly targeting tumor cells." (PMID 38239636, 2023). "The overexpression of tumor galectin-1 is the most significant prognosticator for poor LRPFS." (PMID 35280768, 2022). "Galectin-1 has vital roles in tumorigenesis and tumor development." (PMID 35677161, 2022). "One such example is the interaction of galectin-1, a secretory galactoside-binding protein induced by hypoxia, with the N-glycan part of KDR on cell surface, thereby conferring VEGF-like signaling for tumor-associated angiogenesis." (PMID 36517806, 2022). "In conclusion, our study revealed the expression pattern of tRFs in both tissue and plasma exosomes and identified a novel tRF, tRF-3022b, which may affect CRC tumor growth and M2 macrophage polarization by binding to LGALS1 and MIF." (PMID 36527118, 2022). "Besides, patients with overexpression of tumor galectin-1 had a trend of worse OS (p = 0.066) than those with low expression in multivariable analysis, and worse DMFS (p = 0.035) in univariable analysis." (PMID 35280768, 2022). "In both groups (Fra-2 cl 1 and cl 2), some interesting genes could be identified, e.g., in the Fra-2 cl 1 primary tumours LGALS1, ADRM1, and CTTN, which were upregulated and LUM (Lumican), MAN1A1, and SPARC, which were significantly downregulated." (PMID 34693476, 2022). "Finally, galectin-1 enhances immune evasion of tumor cells by promoting angiogenesis and enhancing cellular metabolism around tumor tissues." (PMID 36428567, 2022). "For example, we described important roles of galectin-1 and galectin-9 in tumor angiogenesis." (PMID 36497271, 2022). "Hence, galectin-1 protein is considered a prognostic indicator for tumor progression in pathological analyses and a target for glycocluster design." (PMID 34482478, 2022). "In addition, patients with overexpression of tumor galectin-1 had the trend of worse OS (HR = 2.80; p = 0.066) in multivariable analysis, and significantly worse DMFS (HR = 2.43; p = 0.035) in univariable analysis." (PMID 35280768, 2022). "Further supporting a tumor-suppressor role for miR-22, oncogenes such as galectin-1 (LGALS1), ezrin (EZR), histone deacetylase 4 (HDAC4) tyrosine 3-monooxygenase/tryptophan 5-monooxygenase (YWHAZ), specificity protein 1 (SP1), and basigin (CD147) were reported to be hepatic targets of miR-22." (PMID 36139435, 2022). "Galectin-1 is important in mediating the immune evasion of tumor cells." (PMID 36428567, 2022). "Indeed galectin-1, -3, -8 and -9 are expressed in GB and the interaction with their respective glycan-carrying molecules blocks the anti-tumor response, thus promoting immunosuppression." (PMID 35682991, 2022). "Tumor cells weaken the function of immune cells by secreting galectin-1." (PMID 35677161, 2022). "None of the evaluated clinicopathological parameters, including stage, grade or tumor location, was significantly associated with low (sum of absent/low score) or high (sum of moderate/high score) galectin-1 expression levels." (PMID 36497271, 2022). "Its transcript was clearly upregulated in tumours resected from select mice injected with Fra-2 cl 1 as well as cl 2 and we were able to detect the expression of LGALS1 by immunohistochemistry both in the tumours and in metastatic cells in the lungs of animals of both Fra-2 overexpressing clones." (PMID 34693476, 2022). "Galectin-1 could directly activate the Hh pathway in the tumor stroma and promote the fibrosis of PDAC." (PMID 36428567, 2022). "Galectin-1 and galectin-3 tumors enhance adaptation to the hypoxic microenvironment by promoting angiogenesis, conversion of tumor cell metabolism to glycolysis, and tumor cell adaptation to metabolic stress." (PMID 36428567, 2022).